LRRK2 (leucine rich repeat kinase 2)
Diseases named in the same sentence as LRRK2 in open-access papers (continued):
Sharing a sentence is not in itself a finding about the gene and the disease.
Parkinson disease (continued). "Mutations segregating with Parkinson's disease reside within the enzymatic core of LRRK2, suggesting that modification of its activity impacts greatly on disease onset and progression." (PMID 25899482, 2015). "In the present study we have analyzed the frequency of the LRRK2 p.G2019S mutation in 154 patients with familial or sporadic Parkinson Disease, including early and late onset patients, and 162 normal controls." (PMID 26600626, 2015). "We also verified that 21 of the LRRK2 interactors are genetically linked to risk for Parkinson’s disease or inflammatory bowel disorder." (PMID 25737818, 2015). "It is now well established that coding changes in LRRK2 are one of the most common causes of Parkinson’s." (PMID 25737818, 2015). "Here, we examined endolysosomal morphology in fibroblasts from Parkinson disease patients with the common LRRK2 G2019S mutation." (PMID 25416817, 2015). "Parkinson’s disease-associated proteins like α-syn, parkin, LRRK2, and DJ-1 have also been reported to activate microglia." (PMID 26217195, 2015). "Human genetics has linked LRRK2 to Parkinson’s disease, Crohn’s disease, multibacillary leprosy, and cancer." (PMID 24981771, 2014). "Mutations in LRRK2, encoding the multifunctional protein leucine-rich repeat kinase 2 (LRRK2), are a common cause of Parkinson disease." (PMID 24275654, 2014). "Mutations in LRRK2 cause a dominantly inherited form of Parkinson’s disease (PD) and are the most common known genetic determinant of PD." (PMID 25288684, 2014). "Mutations in Leucine-Rich Repeat Kinase-2 (LRRK2) result in familial Parkinson's disease and the G2019S mutation alone accounts for up to 30% in some ethnicities." (PMID 25309331, 2014). "This shortcoming can be overcome by the use of the SemRep system which introduces relevant semantic relationships between concepts (e.g., LRRK2 gene causes Parkinson disease)." (PMID 25006672, 2014). "The three main proteins linked to Parkinsonism, α-syn, tau, and LRRK2 all display phosphorylations which are modified in disease." (PMID 25426138, 2014). "Subsequent studies have used C. elegans as a system to examine the function of human LRRK2, a number of which have examined Parkinson’s disease mutations located in the ROC domain." (PMID 24981771, 2014). "The phosphorylation of Prx3 was associated with the increased cell death in neuronal cells by a mitochondrial stress and significantly detected in Parkinson's disease patients with the LRRK2 mutation." (PMID 24672551, 2014). "General demographic data and parkinsonian motor symptoms in patients with LRRK2 G2019S associated Parkinson’s disease, idiopathic Parkinson’s disease and healthy subjects." (PMID 25330404, 2014). "Leucine-rich repeat kinase 2 (LRRK2) mutations are the most common genetic cause of Parkinson’s disease." (PMID 25316291, 2014). "Mutations especially in these GTPase and kinase domains of LRRK2 are the most common causes of heritable Parkinson's disease (PD) and also found in sporadic forms of PD." (PMID 25360523, 2014). "The leucine-rich repeat kinase 2 mutation G2019S in the kinase-domain is the most common genetic cause of Parkinson's disease." (PMID 25107341, 2014). "Leucine-rich repeat kinase 2 (LRRK2) is a multi-domain 280 kDa protein that is linked to Parkinson's disease (PD)." (PMID 25360523, 2014). "Mutations in LRRK2 have been found to be thus far the most frequent cause of late-onset Parkinson’s disease (PD)." (PMID 24847205, 2014). "Missense mutations in the Leucine-Rich Repeat protein Kinase 2 (LRRK2) gene are the most common genetic predisposition to develop Parkinson’s disease (PD)." (PMID 25009464, 2014). "Rab29 (also referred as Rab7L1) is a novel Rab protein, which was recently found to mediate bacterial infection, and modify intraneuronal protein sorting and Parkinson's disease risk through interacting with LRRK2." (PMID 24788816, 2014).
Parkinson disease (continued). "Parkinson’s disease related mutations in the GTPase domain of LRRK2 enhanced the interaction and was shown to increase mitochondria fragmentation." (PMID 24926233, 2014). "Mutations in LRRK2 are associated with the familial form of Parkinson disease but were also linked to inflammatory bowel disease, leprosy, and cancer." (PMID 24465451, 2014). "We report an update about the frequency of major LRRK2 mutations in a large series of consecutive patients with Parkinson's disease (PD), including extensive characterization of clinical features." (PMID 24816003, 2014). "The LRRK2 gene has been associated with both familial and sporadic forms of Parkinson's disease (PD)." (PMID 25243190, 2014). "Related to Parkinson's disease, there was another interesting report that a mutation of leucine rich repeat kinase 2 (LRRK2), where glycine-2019 is mutated to serine, increased the phosphorylation of a mitochondrial Prx3." (PMID 24672551, 2014). "LRRK2 is involved in mitochondrial dysfunction, which is discussed as a cause of Parkinson's disease." (PMID 25360523, 2014). "Loss of ψm was also found in MPP+ treated neurons, skin cells from Parkinson patients with LRRK2 G2019S mutation and cells with deficiency of DJ-1, a gene identified in early-onset recessive parkinsonism." (PMID 24392030, 2013). "The central role of LRRK2 in Parkinson’s disease (PD) has been highlighted by the discovery of autosomal dominant mutations in LRRK2 causing familial PD and the subsequent identification of the LRRK2 locus as a risk factor for sporadic disease." (PMID 24211199, 2013). "Rare missense mutations and more common genetic variability in the LRRK2 (leucine-rich repeat kinase 2) gene are known to be important susceptibility factors to late-onset typical PD (Parkinson's disease)." (PMID 23560750, 2013). "Mutations in the gene encoding leucine-rich repeat kinase 2 (LRRK2) account for up to 13% of familial Parkinson's disease (PD) cases." (PMID 23646112, 2013). "LRRK2 is a large (2527 aa) serine/threonine protein kinase whose mutation can cause Parkinsonism, and is predicted by ARD2 to have repeats in the region 360–494." (PMID 24278209, 2013). "Mutation in the LRRK2 kinase domain is associated with Parkinson’s disease whereas the CD-associated LRRK2 variant results in less functional protein." (PMID 24137160, 2013). "Missense mutations in the leucine-rich repeat kinase 2 gene (LRRK2) are linked to autosomal dominant forms of Parkinson’s disease (PD)." (PMID 23675505, 2013). "The Leucine-rich repeat serine/threonine-protein kinase 2 (LRRK2) variants located on the long arm of chromosome 12 (12q12) are well documented as a common cause for parkinson disease." (PMID 24015287, 2013). "First, and dependent upon elucidation of the role of mutations in LRRK2 in the pathological cascade that leads to Parkinson's disease, will be how to correct their impact." (PMID 23938341, 2013). "Neuronal cells transfected with Parkinson’s disease-associated LRRK2 variants exhibited increased autophagic vacuole formation and accumulation of protein aggregates." (PMID 24137160, 2013). "LRRK2 is associated with various diseases, including Parkinson’s disease, cancer, and leprosy and also known to be associated with susceptibility to the chronic autoimmune Crohn’s disease, which is an inflammatory disorder." (PMID 24015287, 2013). "Although PARK8 is just one of more than a dozen loci linked to Parkinson’s disease, certain lines of evidence indicate that LRRK2 is of special relevance." (PMID 23754980, 2013). "Mutations in the gene encoding leucine-rich repeat kinase 2 (LRRK2) are the most frequent cause of familial Parkinson’s disease (PD)." (PMID 24113872, 2013). "As in Lewy-body Parkinson's disease, nigral degeneration is a typical finding in LRRK2 mutation and is considered to be the pathological substrate of clinical parkinsonism in these patients." (PMID 23664753, 2013).
Parkinson disease (continued). "Tremor is the most commonly recognized initial symptom; indeed LRRK2-associated disease has been categorized by a large collaborative study as an asymmetrical tremor-predominant parkinsonism with bradykinesia and rigidity." (PMID 23938341, 2013). "It has been shown that early onset Parkinson's disease is associated with certain genetic mutations such as Parkin, LRRK2, and PINK1." (PMID 24455416, 2013). "The asymmetry of radioligand uptake for Parkinson's disease with GBA or LRRK2 mutations was greater than that for Parkinson's disease with alpha synuclein, PINK1 or Parkin mutations." (PMID 23935950, 2013). "The most common LRRK2 mutation, G2019S, accounts for as much as 30-40% of Parkinsonism in Ashkenazi Jews and North African Arab-Berber populations." (PMID 24244710, 2013). "Genetic variants of leucine-rich repeat kinase 2 (LRRK2) were reported to alter the risk for Parkinson’s disease (PD)." (PMID 24339985, 2013). "Missense mutations in LRRK2 (leucine-rich repeat kinase 2) are a major cause of PD (Parkinson's disease)." (PMID 23560750, 2013). "We report a case with LRRK2 G2019S mutation clinically diagnosed as Parkinson's disease, with good levodopa response, in which neuropathological analysis revealed nigral degeneration with an absence of Lewy bodies, Alzheimer-type tau, and TDP-43 pathologies." (PMID 23664753, 2013). "Among the 5 identified pathogenic leucine-rich repeat kinase 2 (LRRK2) mutations, G2019S is the most common, and accounts for 1% of sporadic Parkinson's disease and 4% of hereditary parkinsonism worldwide." (PMID 23664753, 2013). "The genetic association identified between LRRK2 and Parkinson’s disease has made it a very attractive drug target for the pharmaceutical industry." (PMID 23799078, 2013). "Leucine-rich repeat kinase 2 (LRRK2) is a large multidomain kinase/GTPase that has been recently linked to three pathological conditions: Parkinson’s disease; Crohn’s disease; and leprosy." (PMID 22594666, 2012). "We discuss the role of leucine-rich repeat kinase 2 in autophagy, and how the deregulations of this degradative mechanism in cells can be implicated in the Parkinson's disease etiology." (PMID 22970411, 2012). "Incredibly, the most common mutation LRRK2 G2019S accounts for up to 40 % of Parkinsonism in populations of certain ethnic descent." (PMID 22647713, 2012). "LRRK2, a Parkinson's disease associated gene, is highly expressed in microglia in addition to neurons; however, its function in microglia has not been evaluated." (PMID 22496842, 2012). "Independent studies identified α-synuclein, Pink1, Parkin, DJ-1, and Leucine-rich repeat kinase 2 (LRRK2) as commonly mutated genes in Parkinsonism." (PMID 22792111, 2012). "LRRK2 is a WD40 protein associated with Parkinson’s disease, and it has been shown that the WD40 domain is required for neuronal cell death." (PMID 22523538, 2012). "One of the key genes in PD is LRRK2, mutations in which have been identified in a large number of families affected by an inherited form of parkinsonism with clinical presentation and disease onset very similar to the more common sporadic syndrome." (PMID 22594666, 2012). "LRRK2 mutations also account for around 2% of sporadic Parkinsonism and two risk factors have been identified in Asian populations." (PMID 22647713, 2012). "Recent studies show that mutations in Leucine Rich Repeat Kinase 2 (LRRK2) are the cause of the most common inherited and some sporadic forms of Parkinson's disease (PD)." (PMID 21390248, 2011). "Mutations in LRRK2 are implicated in Parkinson’s disease (PD), possibly due to a role for this gene in autophagy-mediated clearance of protein aggregates in neurons." (PMID 21994779, 2011). "Dominant mutations in the leucine-rich repeat kinase 2 (LRRK2) gene are the most prevalent cause of Parkinson's disease, however, little is known about the biological function of LRRK2 protein." (PMID 21695257, 2011).
Parkinson disease (continued). "Genetic variants of Leucine-Rich Repeat Kinase 2 (LRRK2) are associated with a significantly enhanced risk for Parkinson disease, the second most common human neurodegenerative disorder." (PMID 21738687, 2011). "Leucine rich repeat kinase 2 (LRRK2) is a Parkinson's disease (PD) gene that encodes a large multidomain protein including both a GTPase and a kinase domain." (PMID 21858031, 2011). "Mutations in the leucine-rich repeat kinase 2 (LRRK2) gene have been linked to dominantly inherited Parkinson's disease (PD)." (PMID 21712955, 2011). "Mutations within the leucine-rich repeat kinase 2 (LRRK2) gene are a common cause of familial and sporadic Parkinson's disease." (PMID 21048939, 2010). "Mutations in LRRK2 (leucine-rich repeat kinase 2) have been identified as major genetic determinants of Parkinson's disease (PD)." (PMID 21060682, 2010). "Mutations in the gene encoding Leucine-rich repeat kinase 2 (LRRK2) are the most common cause of inherited Parkinson's disease (PD)." (PMID 20090955, 2010). "A newly identified familial mutation N1437S, localized within the GTPase domain of LRRK2, further underlines the importance of the GTPase domain of LRRK2 in Parkinson's disease pathogenesis." (PMID 21048939, 2010). "Mutations within LRRK2 contribute to 5-6% of all cases of autosomal-dominant as well as to 1-2% of cases of sporadic Parkinson's disease." (PMID 21048939, 2010). "Even years after the initial description of LRRK2 mutations as a frequent cause of familial Parkinson's disease, only little is known on the normal function of this multidomain protein GTPase and kinase." (PMID 21048939, 2010). "Dominant mutations in leucine-rich repeat kinase 2 (LRRK2) are the most common genetic cause of Parkinson's disease, however, the underlying pathogenic mechanisms are poorly understood." (PMID 20949042, 2010). "For example, mutation of the LRRK2 gene causes Parkinson's disease by enhancing (at least partially) the kinase activity of LRRK2." (PMID 20361056, 2010). "Autosomal dominant missense mutations within the gene encoding LRRK2 (leucine-rich repeat proteinkinase 2) predispose humans to Parkinson's disease." (PMID 20659021, 2010). "Mutations in LRRK2 represent the most common causes of Parkinson's disease (PD) identified to date, but their penetrance is incomplete and probably due to the presence of other genetic or environmental factors required for development of the disease." (PMID 20976090, 2010). "Loss-of-function mutations or DA neuron-specific inactivation of the respective Drosophila homologues of PINK1, Parkin, DJ-1, LRRK2, and HtrA2 can also lead to parkinsonism-like DA cell loss and locomotor defects." (PMID 20522007, 2010). "Mutations in leucine-rich repeat kinase 2 (LRRK2) are the most common genetic cause of Parkinson disease (PD)." (PMID 20041156, 2009). "The core feature of the 356 patients with LRRK2 Gly2019Ser-associated PD was asymmetrical, tremor-predominant parkinsonism with bradykinesia and rigidity that responded to dopamine replacement and functional neurosurgery." (PMID 18539534, 2008). "Respective mutations in five genes—SNCA (α-synuclein), PARK2 (parkin), PARK7 (DJ-1), PINK1, and LRRK2—can cause parkinsonism that resembles idiopathic PD." (PMID 18539534, 2008). "Mutations in the genes PRKN and LRRK2 are the most frequent known genetic lesions among Parkinson's disease patients." (PMID 18211709, 2008). "Mutations within the leucine-rich repeat kinase 2 (LRRK2) gene account for a significant proportion of autosomal-dominant and some late-onset sporadic Parkinson's disease." (PMID 18045479, 2007). "For example, in, the preposition "in" indicates the predicate ASSOCIATED_WITH (having arguments "LRRK2" and "Parkinson disease")." (PMID 16762065, 2006). "Additionally, clinical studies should evaluate the impact of homotaurine on bone density and fracture risk in people with Parkinson’s disease carrying LRRK2 mutations." (PMID 40227236, 2025).
Parkinson disease (continued). "Furthermore, we found that STING-induced autophagy activated Leucine-rich repeat kinase 2 (LRRK2), a protein implicated in Parkinson’s disease, through GABARAPs lipidation." (PMID 39982740, 2025). "Genetic components such as the APOE ε4 allele, which is responsible for Alzheimer’s disease, and mutations in LRRK2, which are responsible for Parkinson’s disease, are now facilitating the development of individualized approaches for neurosurgical or pharmacological treatments." (PMID 40806492, 2025). "Parvalbumin interneurons in the dorsal striatum lose primary cilia in mice and humans harboring Parkinson’s disease–associated, activating mutations in LRRK2 kinase, resulting in loss of hedgehog signaling and decreased production of neuroprotective Neurturin to support dopamine neurons." (PMID 39537338, 2025). "LRRK2 variants are key genetic risk factors for Parkinson’s Disease (PD)." (PMID 40301370, 2025). "LRRK2 is a kinase whose activity is linked to Parkinson’s disease." (PMID 39812709, 2025). "Similarly, impairments in Rab8a or Rab10 function result in endolysosomal trafficking deficits that mirror those observed with the pathogenic G2019S mutation in LRRK2, a mutation linked to Parkinson’s disease, and are accompanied by a diminished Rab7 activity." (PMID 40659647, 2025). "Genetic studies have suggested that Parkinson's disease patients with LRRK2 mutations are more likely to exhibit the PIGD phenotype, while those who are homozygous for the H1 haplotype of the microtubule-associated protein tau (MAPT) gene tend to present with a non-tremor-dominant phenotype." (PMID 40401020, 2025). "The identification of the STING pathway as a robust endogenous activator of LRRK2 suggests that upstream stimuli that activate STING may also contribute to Parkinson’s disease risk." (PMID 39812709, 2025). "Recent cryo-electron microscopy studies in cell lines overexpressing Parkinson’s disease-associated LRRK2 suggest microtubule surfaces may regulate kinase activity by stabilizing different LRRK2 conformations." (PMID 40425780, 2025). "The first example is the leucine-rich repeat kinase 2 (LRRK2) associated with Parkinson's disease." (PMID 41192797, 2025). "Aberrant JIP4-TMEM55B-dependent control of lysosomal cystine efflux may thus contribute to the effects of LRRK2 gain-of-function mutations that give rise to Parkinson’s disease." (PMID 40661466, 2025). "Mutations of LRRK2 have been linked to Parkinson’s disease and Crohn’s disease." (PMID 39982740, 2025). "Other genes have also been implicated, such as LRRK2, which is an established cause of familial Parkinson’s disease, but may also contribute to other forms of neurodegeneration through overstabilisation of the actin cytoskeleton." (PMID 40138021, 2025). "Based on these findings, it is likely that environmental stressors can accelerate parkinsonism in patients harbouring the LRRK2 R1628P risk variant, more so than the general population, and especially when environmental insults start at the beginning of the organism’s development." (PMID 40332013, 2025). "Parkinson’s disease (PD) pathogenic mutations in leucine-rich repeat kinase 2 (LRRK2) are associated with endolysosomal dysfunction across cell types, and carriers of LRRK2 mutations variably present with phosphorylated tau and α-synuclein deposits in post-mortem analysis." (PMID 40661559, 2025). "Meanwhile, trichloroethylene is an environmental risk factor for Parkinson’s disease that has been linked to lysosomes and LRRK2 hyperactivation via mechanisms that may converge on the pathways that we have defined here." (PMID 41332754, 2025). "Mitochondrial dysfunction is present in both idiopathic Parkinson’s disease (iPD) and LRRK2-related Parkinson’s disease (LRRK2-PD), but distinct mitochondrial pathologies may underlie these disorders." (PMID 40080233, 2025).